MUC6 (mucin 6, oligomeric mucus/gel-forming (gene/pseudogene))
Diseases named in the same sentence as MUC6 in open-access papers (continued):
Sharing a sentence is not in itself a finding about the gene and the disease.
tumor (continued). "In contrast, three membrane‐bound MUCINs (MUC1, MUC13, and MUC15), one atypical MUCIN (EMCN), and one secretion MUCIN (MUC6) were significantly downregulated in the tumor samples (p < 0.05)." (PMID 34327857, 2021). "GA-FGM is occasionally accompanied by tumor components consisting of mucous neck cells or pyloric gland-like (MUC6-positive mucous cell) differentiation." (PMID 34268625, 2021). "Of interest was the significantly lower expression by tumour cells (in 9/52 cases, 17%) of MUC6, a specific marker of pyloric and Brunner glands." (PMID 33963925, 2021). "As a potential tumor suppressor, the overexpression of MUC6 is related to favorable outcomes in CRC patients." (PMID 32695780, 2020). "MUC5AC expression was seen in tumour cells in the superficial part of the gastric wall, whereas tumour cells positive for MUC6 or PCS III were more frequently found in deeper parts of the wall." (PMID 32488651, 2020). "Two secreted mucin mRNA (MUC5AC and MUC5B) were also increased in tumor samples (p < 0.01), whereas MUC6 was decreased in tumor samples compared to the normal pancreas." (PMID 33182511, 2020). "Immunohistochemistry showed that tumor cells diffusely expressed pepsinogen -I and MUC6, which suggested that GA-FG originated from the chief cell of the mucosal layer rather than the foveolar cells of the epithelium." (PMID 33097069, 2020). "Another gastric mucus, MUC6 is mainly expressed in glandular epithelial cells and is absent in many tumors, predicted to have a tumor-suppressive role in the occurrence and development of CRC." (PMID 32695780, 2020). "Of the 479 LGG tumor samples, 134 (28%) contain mutations in both IDH1 and MUC6, while 5 (1.5%) of 333 normal tissue samples contain a mutation in both these genes." (PMID 30700767, 2019). "In another study, MUC6 expression was associated with the CpG island methylator phenotype (CIMP) of CRC and tumorigenesis via the serrated neoplasia pathway." (PMID 31091244, 2019). "Descriptions of some of the clinical cases indicate coexistence of strong MUC5AC-positivity in perihilar CCs and extensive MUC6-positivity in C-P neoplasm of PBGs, suggesting different origin of these neoplasms." (PMID 30875782, 2019). "Immunohistochemically, the tumor showed scattered positivity for pepsinogen I and H+/K+-ATPase and strong positivity for MUC6." (PMID 30212986, 2018). "Within the group of 17 proteins, four exhibited the most pronounced expression difference: IGFBP7, S100A9 and IL-10 were found strongly up-regulated in tumor, while MUC6 was markedly less abundant compared to the reference tissue." (PMID 27600085, 2016). "According to their and other literature data, MUC6 and MUC5AC expression is strongly associated with features of the serrated neoplasia pathway." (PMID 27298226, 2016). "MUC2, MUC5AC, and MUC6 were significantly associated with MMR status and tumor border configuration." (PMID 27298226, 2016). "Immunohistochemically, as in the present case, the tumour typically expresses MUC6 and variably MUC5AC." (PMID 23206236, 2012). "However, we observed a slightly but statistically significant overexpression of PD-L1 in cases presenting MUC6 staining in at least 50% of tumor cells." (PMID 39755998, 2025). "The tumor cells showed positive expression of MUC-6, CAIX, MUC5AC, HNF-1β, MUC-1, CK7, and Pax-8." (PMID 40018404, 2025). "Some researchers insist that MUC6 serves as a tumor marker in gastric and other cancers." (PMID 38732035, 2024). "The analysis identified 51 tumor entities with at least occasional MUC6 expression." (PMID 37057870, 2023). "In principle, MUC6 IHC would provide the highest level of diagnostic information with respect to tumor types that are always MUC6 negative." (PMID 37057870, 2023).
tumor (continued). "With this aim, we designed this retrospective study to demonstrate profiles of MUC expression (MUC1, MUC2, MUC5AC, and MUC6) of different histologic patterns within the same tumor among pulmonary adenocarcinomas and investigate correlations of MUC expression with clinicopathologic features." (PMID 36367122, 2023). "We designed this retrospective study to demonstrate profiles of MUC expression (MUC1, MUC2, MUC5AC, and MUC6) of different histologic patterns within the same tumor among pulmonary adenocarcinomas and investigate correlations of MUC expression with clinicopathologic features." (PMID 36367122, 2023). "At least a weak MUC6 positivity was seen in 50 of 119 (42%) tumor entities." (PMID 37057870, 2023). "Moreover, the results of MUC6 knock-down assay and CRISPR-induced MUC6 mutations showed that MUC6 inhibited tumor aggression via autophagy-dependent β-catenin degradation while its mutations attenuated tumor-suppressive effects of MUC6." (PMID 35574418, 2022). "It reveals that MUC6 plays an important tumor-suppressive role in WT, and thus may be a promising therapeutic target for WT." (PMID 35574418, 2022). "As β-catenin is essential for WT tumorigenesis, MUC6 may affect tumor cell behaviors via autophagy-β-catenin pathway." (PMID 35574418, 2022). "MUC6 acted as a tumor suppressive gene through autophagy dependent β-catenin pathway." (PMID 35574418, 2022). "On the other hand, the same analyses in patients with well- to moderately differentiated tumors showed that MUC6 tumor expression and age of disease onset could be independent predictors in GBC patients." (PMID 33494186, 2021). "Only a limited, non-significant association was observed between the CK7 and MUC5AC expression by tumour cells (p=0.16, Fisher’s exact test), while a significant association was found between MUC5AC and MUC6 expression (p=0.003), with all but one MUC6-positive cancers also showing MUC5AC reactivity." (PMID 33963925, 2021). "Tumor cells were positive for pepsinogen-I, MUC6, SYN, and CD56." (PMID 33097069, 2020). "Secretory mucins (MUC2 and MUC6) and the mucus might also act as a barrier to cancerous extension and decrease the aggressiveness of the tumor biology." (PMID 27102151, 2016). "Here, we evaluated the tumor morphology and immunohistochemical expression of CDH17 and CLDN18 in 25 CD-SBNs and potential relationships with gastric differentiation as indicated by MUC5AC and MUC6 immunohistochemistry, wnt pathway mutations, and mismatch repair gene protein immunohistochemistry." (PMID 39164422, 2025). "Finally, MUC6-autophagy-β-catenin pathway affects tumor behaviors in in-vitro and in-vivo assays." (PMID 35574418, 2022). "Therefore, regarding MUC1, MUC2, MUC5AC, and MUC6, the most important point seems to be represented by the simultaneous and the correct use of all four of these mucins, and the integration of their expression pattern with tumor morphology." (PMID 35583805, 2022). "Similarly, mutations at F1989 of MUC6, which occur most frequently in both tumor and normal samples are unlikely to be carcinogenic." (PMID 30700767, 2019). "In particular, CK20, MUC2, MUC5AC, MUC6 and β-catenin showed disparate expression patterns that may in part be ascribed to clinicopathologic factors such as tumor location, mucinous components, differentiation, and MSI-status, conceivably reflecting diverse underlying genetic mechanism(s)." (PMID 28824332, 2017). "Tumour cells with high TFF1 expression (MP2 state) were clustered mainly at the top of the mucosal layer, while MUC6‐positive cells (MP6 state) were predominantly aggregated around the neck of the gland lumen." (PMID 40292733, 2025). "In specific, study reported that tumor cells showed expression levels of MUC1 (77%), MUC2 (2%), MUC5B (63%), MUC5AC (36%) and MUC6 (21%)." (PMID 40655139, 2025). "Immunohistochemistry of the tumor cells revealed positivity for MUC5AC and MUC6 and negativity for MUC2 and CDX2." (PMID 41256328, 2025).
tumor (continued). "Immunohistochemically, tumor cells were positive for both MUC5AC and MUC6, while pepsinogen-I and H+/K+-ATPase were both negative." (PMID 38583117, 2024). "By delving deeper into the characterization of GC cells, we identified 6 specific tumour cell subtypes: C0 PSCA+ tumour cells, C1 CLDN7+ tumour cells, C2 UBE2C+ tumour cells, C3 MUC6+ tumour cells, C4 CHGA+ tumour cells and C5 MUC2+ tumour cells." (PMID 38894657, 2024). "The present study aimed to analyse the sequence of some selected fragments of MUC6 and MUC16 genes in the tumour and the margin samples obtained from the OPSCC patients." (PMID 37504272, 2023). "The present study aimed at the analysis of the sequence of selected MUC6 and MUC16 gene fragments in the tumour, as well as the margin, samples obtained from 18 OPSCC patients." (PMID 37504272, 2023). "Immunohistochemically, tumor cells were diffusely positive for CK7, MUC6 and CA-IX, but focally positive for CK20 and CDX2." (PMID 31279344, 2019). "The tumor was positive for cytokeratin (CK)-7 and CK-20, and focally positive for mucin (MUC) 5 AC and MUC6." (PMID 30043132, 2018). "Immunohistochemical analysis revealed that the tumor was positive for cytokeratin (CK)-7 and CK-20, and focally positive for mucin (MUC) 5AC and MUC6." (PMID 30043132, 2018). "Immunohistochemical staining revealed positivity of the tumor cells for Pan-CK, CK7, CK8/18, MUC1, MUC6, CD10, carbonic anhydrase IX and EMA." (PMID 24443801, 2014). "The normal gastric mucosa isolated from tumor-affected stomachs was divided into surface versus gland material and thereby MUC5AC was separated from MUC6." (PMID 22563496, 2012). "We examined histological phenotype of tumors of AFPC or NEC containing the composite tumor by evaluating immunohistochemical expressions of MUC2, MUC5AC, MUC6, CDX2, and SOX2." (PMID 22482081, 2012). "Taking into account the expression combinations of HGM, MUC6, MUC2 and CD10, the incidence of G-phenotype tumours was significantly higher in the peritoneal recurrence group than in the control group." (PMID 15354218, 2004). "In four patients, tumor cells showed diffuse strong positivity for MUC6, but normal gastric epithelial cells were negative." (PMID 40692725, 2025). "After cellular annotation of the 6 tumour cell types based on marker gene expression, we were able to identify the following: C0 PSCA+ tumour cells, C1 CLDN7+ tumour cells, C2 UBE2C+ tumour cells, C3 MUC6+ tumour cells, C4 CHGA+ tumour cells and C5 MUC2+ tumour cells." (PMID 38894657, 2024). "The hierarchical cluster analysis performed for the identified variants revealed no significant similarities nor mutation patterns in the MUC6 coding sequence or both MUC6 and MUC16 corresponding to the tumour or margin groups." (PMID 37504272, 2023). "The fact that none of the analyzed tumor categories showed MUC6 positivity in more than 40% of cases makes it clear that the absence of MUC6 immunostaining cannot exclude any tumor entity." (PMID 37057870, 2023).
tumor (continued). "It is of note that a considerable fraction of these tumor types is derived from epithelial tissues (i.e., colon mucosa, endometrium) that do not regularly express MUC6." (PMID 37057870, 2023). "Overall, mRNA expression of MUC1, MUC5AC, and MUC6 was significantly higher in the paired adjacent non-tumor tissues compared to the tumor and FD tissues." (PMID 37085819, 2023). "Given that the rate of MUC6 positivity does not exceed 40% in any tumor entitity, MUC6 expression analysis is not suited for the distinction of tumors of different sites of origin." (PMID 37057870, 2023). "Moreover, the immunohistochemical staining test for tumor area was positive for MUC5AC and MUC6, also its pattern was different from that of normal duodenal mucosa." (PMID 36781821, 2023). "In the present study, we first analyzed the tumor and adjacent non-tumor tissues of the GC patient cohorts and the biopsy tissues of the FD patients to measure the relative mRNA expression of gastric (MUC1, MUC5AC, MUC6) and intestinal (MUC2, MUC4, MUC13) mucins." (PMID 37085819, 2023). "Immunohistochemical analysis of both low- and high-grade lesions showed MUC6 expression in tumor cells irrespective of histological grade." (PMID 38062108, 2023). "As MUC6 is usually not expressed in normal colorectal epithelial cells, our findings suggest that a neo‐expression of MUC6 can parallel tumor progression in at least some tumor types." (PMID 37057870, 2023). "Notably, S100P + cells accounted for 91.14% of total tumor cells from these seven iCCAs and displayed more representative and extensive-expression compared with the other markers (MUC5AC: 42.37%, and MUC6: 22.97%)." (PMID 35347134, 2022). "The mucin markers MUC5AC, MUC6, MUC2 and CD10 were considered necessary, although there is no consensus on the number of markers that should be used to define a mucin phenotype or the percentage of tumour cells that must be stained." (PMID 34256780, 2021). "Tumor immunohistochemical analyses were presented as follows: Inhibin-α (-), ER (-), Vimentin (mesenchyme +), CK7 (+), CK19 (+), CK20 (−), CEA (−), MUC-1 (+), MUC-5AC (+), MUC-6 (+), MUC-2 (−), S-100p (focal+), and Ki-67 (12% +)." (PMID 33592896, 2021). "Results revealed that the primary tumor had increased diffuse expression of MUC5AC and MUC6." (PMID 34264404, 2021). "Immunohistochemically, the tumor cells were positive for MUC6 and MUC5AC and negative for intestinal-type markers such as MUC2, CD10 and CDX2." (PMID 34160413, 2021). "These neoplasms are usually negative for ER, PR, vimentin, MUC6, GATA3, and CK20, but can be positive for CAIX, HNF1beta, and Napsin A. The intestinal subtype can be positive for CDX2 and CK20 28,39." (PMID 33570865, 2021). "We observed high MUC2 expression (a marker of intestinal type gastric cancer) in JSC15-3 cells and high MUC5AC and MUC6 expression (markers of stomach type gastric cancer) in JSC17-7 cells, which are consistent with differentiation status of original tumour tissues." (PMID 31607750, 2019). "The lack of MUC2, MUC5B, superficial MUC6 and sialylation of non-tumor samples confirms the pathologist's report stating that these specimens were normal." (PMID 22563496, 2012). "The survival rates were not significantly different when patients had or had no expression of MUC1, MUC2, MUC5AC, or MUC6 in tumor." (PMID 22027009, 2011). "Tumours were classified into gastric (G), gastric and intestinal mixed (GI), intestinal (I) or unclassified (UC) phenotypes according to the immunopositivity of HGM, MUC6, MUC2 and CD10 stainings." (PMID 15354218, 2004). "Similarly, altered expression of MUC4 and MUC6 has been reported in CRC and may influence tumor aggressiveness and patient outcomes." (PMID 39682117, 2024).
tumor (continued). "Besides MUC2 and MUC5AC, other mucins, such as MUC1, MUC4, and MUC6, may also be dysregulated in CRC and contribute to tumor progression." (PMID 39682117, 2024). "Our findings do not suggest a major role of MUC6 IHC for the distinction of tumor entities." (PMID 37057870, 2023). "Of note, the only patient with a diagnosis of small‐cell lung cancer and RNA data (Patient 4) had RNA profiles from two tumor sites that were similar to each other and distinct from the other NSCLC tumors with higher levels of several mucins and surfactant proteins (MUC4, MUC5B, MUC6, SFTPB)." (PMID 31747139, 2020). "Anti-MUC5B and anti-MUC6 antibodies did not stain PAC120 tumours (data not shown)." (PMID 14760390, 2004). "In addition, immunostaining of the same area showed that MUC5AC, which stained the gastric crypt epithelium, was diffusely positive in the intramucosal and tumor-infiltrated area, whereas MUC6 was negative to partially positive in the mucosa and positive in approximately 50% of the infiltrated area." (PMID 36781821, 2023). "Recently, a new term, intracholecystic tubular non-mucinous neoplasm (ICTN), was proposed for a type of preinvasive tumor-forming gallbladder neoplasm composed of small, non-mucinous tubules, often with squamoid morules and cholesterolosis in the background, showing diffuse MUC6 expression." (PMID 35204432, 2022). "However, the tumor sample containing MUC6 did not contain α1,4-GlcNAc." (PMID 22563496, 2012). "On immunohistochemical analysis, the tumor was positive for MUC5AC and MUC6 and negative for MUC2 and CDX2, indicating a gastric phenotype." (PMID 41256328, 2025). "Immunohistochemical staining revealed that the tumor cells were positive for MUC5AC and MUC6 and negative for Pepsinogen I and H + /K + -ATPase." (PMID 38583117, 2024). "Immunohistochemically, the tumor cells were positive for intestinal markers, namely MUC2 and CD10, and negative for gastric markers, namely MUC5AC and MUC6." (PMID 35898822, 2022). "Intraductal pancreatic mucinous neoplasm (IPMN) often shows positivity for MUC5 and MUC6 in the gastric and pancreaticobiliary types and positivity for MUC2 and MUC5 in the intestinal type, but these markers were all negative in this tumor." (PMID 34940081, 2021). "Immunohistochemically, tumor cells were positive for Vimentin (mesenchyme), CK7, CK19, MUC-1, MUC-5AC, MUC-6, S-100p (focal), Ki-67 (12%), and negative for Inhibin-α, ER, CK20, CEA, and MUC-2." (PMID 33592896, 2021). "This study confirmed the expression of MUC5AC and MUC6, as well as negative expression of MUC1 and MUC2 throughout the tumour, with the final diagnosis indicating mucin producing HCC." (PMID 30875782, 2019). "Immunohistochemical analysis showed positive staining for pepsinogen I, H+/K+-adenosine triphosphatase, MUC6, and MUC5AC and negative staining for MUC2 and CD10, indicating tumor differentiation into fundic gland mucosa." (PMID 30212986, 2018). "Immunohistochemical analysis (IHC) revealed that those tumor cells tested positive for CK7, CK20 (weakly), MUC5AC, CEA, and CA19-9 and negative for MUC2, MUC6, and CDX2." (PMID 25386374, 2014). "Immunohistochemical analysis revealed that these tumor cells tested positive for CK7, CK20 (weakly), MUC5AC, MUC6, CDX2 (patchy), CEA, and CA19-9 and negative for MUC2, ER, and PgR." (PMID 25386374, 2014). "Essentially all the tumor cells demonstrated strong cytoplasmic MUC1 staining, but were negative for MUC2, MUC4, MUC5AC and MUC6." (PMID 20550696, 2010).